ESS2 (ess-2 spliceosome associated protein)
Description:
May be involved in pre-mRNA splicing.
Synonyms: DGS-H; DGCR13; DGCR14; DGSH; DGSI; ES2; Es2el; ESS-2; bis1; DGS-I
Tractability: Small molecule: a structure with a bound ligand is known. PROTAC: UniProt records ubiquitination sites on it; ubiquitination databases record sites on it.
Gene: Protein-coding gene on chromosome 22 (19,130,279 to 19,144,684, reverse strand). Ensembl gene ENSG00000100056.
Subcellular location: Nucleus
Subcellular location (Human Protein Atlas): Nucleoplasm
Gene Ontology:
Molecular function: protein binding
Biological process: mRNA splicing, via spliceosome; nervous system development
Cellular component: catalytic step 2 spliceosome; nucleus
Genetic constraint (gnomAD): Loss-of-function variants: 31 observed, 49.59 expected, observed/expected ratio (o/e) 0.63, 90% interval 0.47 to 0.84. The upper end of that interval is the gene's LOEUF score, 0.84, which puts it in group 3 of 6, group 1 being the genes least tolerant of losing a copy. Missense variants: 602 observed, 635.79 expected, observed/expected ratio (o/e) 0.95, 90% interval 0.88 to 1.01. Synonymous variants: 285 observed, 259.85 expected, observed/expected ratio (o/e) 1.1, 90% interval 1 to 1.21.
Homologues: Orthologues: chimpanzee ESS2 (99% identical), macaque ESS2 (99% identical), dog ESS2 (95% identical), rabbit ESS2 (94% identical), rat Ess2 (94% identical), mouse Ess2 (93% identical), pig ESS2 (93% identical), guinea pig ESS2 (93% identical), tropical clawed frog ess2 (67% identical), zebrafish ess2 (62% identical), Drosophila melanogaster Es2 (32% identical), Caenorhabditis elegans ess-2 (30% identical).
Diseases named in the same sentence as ESS2 in open-access papers:
ESS2 is named in the same sentence as 14 diseases in open-access papers, as found by Europe PMC text mining. Sharing a sentence is not in itself a finding about the gene and the disease. The quoted sentences say what the papers report.
22q11.2 deletion syndrome (4 papers, 2010 to 2025). 22q11.2 deletion syndrome (DS) is a chromosomal anomaly which causes a congenital malformation disorder whose common features include cardiac defects, palatal anomalies, facial dysmorphism, developmental delay and immune deficiency. "In humans, the ESS2 gene was first cloned as an expression sequence tag located in the 22q11.2 locus, which is related to the 22q11.2 deletion syndrome (22q11.2DS; also known as DiGeorge syndrome or CATCH 22 syndrome) by two groups independently." (PMID 40362295, 2025). "ESS2 (ess-2 splicing factor homolog, also known as DGCR14 or DGS-I) is a member of the deletion gene cluster in the 22q11.2 deletion syndrome (22q11.2DS, also known as DiGeorge syndrome or CATCH 22 syndrome)." (PMID 40362295, 2025).
schizophrenia (4 papers, 2010 to 2025). A major psychotic disorder characterized by abnormalities in the perception or expression of reality. "ESS2 has also been reported to function in the nervous system, including SNPs that have been associated with suicide and schizophrenia, as mentioned in 1.3." (PMID 40362295, 2025). "Mutations in the ESS2 promoter region have also been reported to be associated with schizophrenia." (PMID 40362295, 2025). "Several molecules in PHR protein signaling pathways also are associated with schizophrenia and autism, including the Tuberous Sclerosis Complex, FSN-1/Fbxo45, and ESS-2/DGCR14." (PMID 26464359, 2015).
prostate carcinoma (2 papers, 2023 to 2025). A carcinoma that arises from epithelial cells of the prostate gland. "ESS2 tends to be highly expressed in prostate cancer patients, and expression levels of some ESS2 target genes, such as LIF, WNT5A, and TGFB1, were significantly correlated with ESS2 levels in prostate cancer patients." (PMID 40362295, 2025). "Since ESS2 associates with the chromatin remodeling factor BAZ1B12, there arises the possibility of ESS2 regulating chromatin remodeling factors in prostate cancer cells." (PMID 37524814, 2023). "Overall, these findings identified ESS2 acts as a transcriptional coregulator in prostate cancer and ESS2 can be novel epigenetic therapeutic target for CRPC." (PMID 37524814, 2023). "We found that ESS2 regulated PC3 cell proliferation by controlling the expression levels of prostate cancer-related genes." (PMID 37524814, 2023). "Among CHD1 target genes, immediate early response 3 (IER3), leukemia inhibitory factor (LIF), and colony stimulating factor 2 (CSF2) were significantly correlated with ESS2 expression in patients with prostate cancer." (PMID 37524814, 2023). "To elucidate the mechanism through which ESS2 affected prostate cancer proliferation, we performed microarray analysis of PC3-shC and PC3-shESS2 cells." (PMID 37524814, 2023). "Immunofluorescence staining showed that ESS2 protein was highly expressed in androgen-independent prostate cancer cell lines (DU145 and PC3)." (PMID 37524814, 2023). "ESS2 is also highly and frequently expressed in cancer cells, including prostate cancer cells." (PMID 37524814, 2023). "Elucidation of the effects of ESS2 on the expression of prostate cancer-related genes is necessary." (PMID 37524814, 2023). "In summary, we demonstrated the roles of ESS2 in prostate cancer progression for the first time." (PMID 37524814, 2023). "In this study, we aimed to elucidate the role of ESS2 in prostate cancer." (PMID 37524814, 2023). "Our results demonstrated that ESS2 was a critical regulator of prostate cancer proliferation." (PMID 37524814, 2023). "Thus, our results showed that ESS2-dependent WNT5A expression may affect prostate cancer progression." (PMID 37524814, 2023). "We examined ESS2 mRNA expression levels in formalin-fixed paraffin-embedded (FFPE) human normal prostate (Normal) and human prostate cancer (PCa) tissues (n = 5 and 21, respectively)." (PMID 37524814, 2023). "Next, we evaluated correlations between ESS2 and CHD1 target gene expression in patients with prostate cancer using the R2 database." (PMID 37524814, 2023). "A recent study reported that ESS2 regulated prostate cancer proliferation primarily through the NF-κB/CHD1 pathway and that ESS2 knockdown lowered histone H3K36 trimethylation levels on the target gene promoters in castration-resistant prostate cancer (CRPC) cells." (PMID 40362295, 2025). "To this end, we established ESS2-knockdown PC3 prostate cancer cells and found that these cells showed reduced proliferation accompanied by aberrant mRNA expression of nuclear factor (NF)-κB/CHD1 and prostate cancer-related genes." (PMID 37524814, 2023). "Although the inhibitory effects of IFN-α and -β on prostate cancer are milder than those of IFN-γ28, these results suggested that ESS2-dependent type I IFN target genes may regulate prostate cancer progression." (PMID 37524814, 2023). "Interestingly, TGF-β1 mRNA levels were downregulated in PC3-shESS2 cells, and ESS2 and TGF-β1 expression levels were significantly correlated in patients with prostate cancer." (PMID 37524814, 2023). "Microarray analysis revealed that ESS2 regulated mRNA levels of chromodomain helicase DNA binding protein 1 (CHD1)-related genes and other cancer-related genes, such as PPAR-γ, WNT5A, and TGF-β, in prostate cancer." (PMID 37524814, 2023). "We also observed correlations between ESS2 and CYP24A1 expression in patients with prostate cancer." (PMID 37524814, 2023).
prostate carcinoma (continued). "Furthermore, we examined ESS2 protein levels in prostate cancer cell lines (LNCaP, CRW22Rv1, DU145 and PC3) and ESS2 highly expressing cells (HEK293 cells) by western blotting." (PMID 37524814, 2023). "ESS2 mRNA levels were upregulated in prostate cancer (median: Normal = 2.39 × 10–5, PCa = 12.8 × 10–5)." (PMID 37524814, 2023). "Furthermore, RT-qPCR showed that WNT5A mRNA levels were decreased in PC3-shESS2 cells, and a correlation was observed between ESS2 and WNT5A expression in patients with prostate cancer." (PMID 37524814, 2023). "Because ESS2 regulates numerous genes involved in prostate cancer, the discovery of ESS2-regulated molecules may contribute to the development of novel molecular targeted therapies for prostate cancer." (PMID 37524814, 2023). "Moreover, ESS2 expression was highly correlated with adenosine deaminase acting on RNA (ADAR), IFN-inducible transmembrane protein (IFITM) 2, and IFITM3 in patients with prostate cancer." (PMID 37524814, 2023).
autoimmune disease (1 paper, 2025). A disorder resulting from loss of function or tissue destruction of an organ or multiple organs, arising from humoral or cellular immune responses of the individual to their own tissue constituents. "ESS2 knockout mice show embryonic lethal in the early stage, and recent studies show the association of ESS2 with cancer, autoimmune disease, and neurodevelopmental disorders." (PMID 40362295, 2025).
cancer (3 papers, 1995 to 2025). A tumor composed of atypical neoplastic, often pleomorphic cells that invade other tissues. "Since the genes targeted by ESS2 in cancer cells and T cells are different, ESS2 must regulate transcription factors in a cell-dependent manner." (PMID 40362295, 2025). "Since ESS2 is also associated with another chromatin remodeling factor (BAZ1B), ESS2-mediated regulation in cancer seems to be complex and to involve chromatin structure." (PMID 40362295, 2025). "Overall, ESS2, which is highly and frequently expressed in cancer tissue, may be a candidate of molecular target therapies for CRPC." (PMID 37524814, 2023). "Based on these results and ESS2 expression in cancer tissues from Protein Atlas data, we hypothesized that Ess2 might also play an important role in cancer cells." (PMID 37524814, 2023). "ESS2 regulates cancer progression, PPAR-γ and VDR responses, and EMT signaling in PC3 cells." (PMID 37524814, 2023). "Thus, ESS2-dependent alterations in CHD1 recruitment can regulate genome-wide gene expression in cancer." (PMID 37524814, 2023). "Firstly, it is not known which domains of ESS2 are essential for cancer proliferation." (PMID 40362295, 2025). "Interactions among ESS2, BAZ1B, and RSK2 may mediate chromatin organization in cancer." (PMID 37524814, 2023).
tumor (3 papers, 2000 to 2023). "ESS2-knockdown PC3 cells dramatically inhibited proliferation in tumor xenografts in nude mice." (PMID 37524814, 2023).
immune diseases (1 paper, 2023). "By contrast, CD4+ T cells from Ess2-knockout mice show aberrant expression related to metabolism and immune diseases (GEO dataset: PRJNA575280)." (PMID 37524814, 2023).
ESS2 also shares sentences with these, for which no sentence is quoted: renal cell cancer (2 papers); autism (1); glioblastoma (1); Intellectual disability (1); neurodevelopmental disorder (1); Parkinson’s (1); tuberous sclerosis (1).